NOP16 (NOP16 nucleolar protein)
Synonyms: HSPC111; HSPC185; LOC51491
Tractability: Small molecule: a structure with a bound ligand is known. PROTAC: UniProt records ubiquitination sites on it; ubiquitination databases record sites on it; its protein half-life has been measured.
Gene: Protein-coding gene on chromosome 5 (176,383,933 to 176,388,927, reverse strand). Ensembl gene ENSG00000048162.
Subcellular location: Nucleus, nucleolus
Subcellular location (Human Protein Atlas): Nucleoli
Gene Ontology:
Molecular function: RNA binding
Biological process: ribosomal large subunit biogenesis
Cellular component: nucleolus
Genetic constraint (gnomAD): Loss-of-function variants: 10 observed, 19.85 expected, observed/expected ratio (o/e) 0.5, 90% interval 0.31 to 0.86. The upper end of that interval is the gene's LOEUF score, 0.86, which puts it in group 3 of 6, group 1 being the genes least tolerant of losing a copy. Missense variants: 166 observed, 202.92 expected, observed/expected ratio (o/e) 0.82, 90% interval 0.72 to 0.93. Synonymous variants: 66 observed, 72.36 expected, observed/expected ratio (o/e) 0.91, 90% interval 0.75 to 1.12.
Homologues: Orthologues: chimpanzee NOP16 (100% identical), dog NOP16 (96% identical), pig NOP16 (92% identical), rabbit NOP16 (92% identical), mouse Nop16 (91% identical), rat Nop16 (91% identical), guinea pig NOP16 (88% identical), tropical clawed frog nop16 (54% identical), zebrafish nop16 (47% identical), Drosophila melanogaster CG11563 (30% identical), Caenorhabditis elegans nol-16 (29% identical).
Diseases named in the same sentence as NOP16 in open-access papers:
NOP16 is named in the same sentence as 11 diseases in open-access papers, as found by Europe PMC text mining. Sharing a sentence is not in itself a finding about the gene and the disease. The quoted sentences say what the papers report.
breast carcinoma (3 papers, 2008 to 2017). "NOP16, or HBV pre-S2 trans-regulated protein 3, is revealed to be an estrogen and c-Myc target gene which is upregulated in breast cancer and associated with poor prognosis of breast cancer patients." (PMID 25577646, 2015).
NOP16 also shares sentences with these, for which no sentence is quoted: cancer (11 papers); colorectal cancer (5); tumor (3); colon cancer (1); gastric cancer (1); hemangioma (1); lymph node metastasis (1); ovarian carcinoma (1); pancreatic cancer (1); prostate carcinoma (1).